LEP (leptin)
Diseases named in the same sentence as LEP in open-access papers (continued):
Sharing a sentence is not in itself a finding about the gene and the disease.
breast cancer (continued). "In particular, LEP has been demonstrated to enhance aromatase expression in MCF-7 breast cancer cells, and to be strictly involved in estrogen receptor (ER) activity modulation, through the existing crosstalk between LEP and ERα." (PMID 36291602, 2022). "Regarding leptin, elevated levels in obese individuals seem to pose a particular problem due to the overexpression of leptin receptors in breast cancer patients." (PMID 36381753, 2022). "Studies have identified genetic variants of LEP and LEPR correlated with susceptibility of various malignant tumors, including breast cancer." (PMID 35223490, 2022). "Our current study aimed at determining the influence of single-nucleotide polymorphisms (SNPs) in the genes coding for LEP and LEPR on breast cancer risk." (PMID 35223490, 2022). "These discoveries open exciting opportunities for future investigations on how glutamine metabolism in the endothelium affects leptin and leptin receptor in breast cancer." (PMID 36381236, 2022). "Adiponectin has been shown to counteract the effect of leptin by inhibiting leptin-induced migration and invasion in breast cancer." (PMID 36292657, 2022). "In vivo studies in mice (MMTV-Wnt-1) have shown elimination of tumor growth as well as breast cancer stem cell population suppression after leptin signaling inhibition." (PMID 36077676, 2022). "Many mechanisms appear to be involved in the correlation between obese-related LEP activity and breast cancer carcinogenesis." (PMID 36291602, 2022). "LEP signaling cascade promotes breast cancer cell proliferation, migration, and invasion through the activation of MAPK, PI3K/AKT, JAK2/STAT pathways, and EMT, irrespective of BC subtypes, primarily in post-menopausal women." (PMID 36291602, 2022). "The prognostic value of LEP expression in breast cancer was explored using the PrognoScan database and R2: Kaplan–Meier Scanner." (PMID 34414945, 2021). "TILs are considered the most relevant part of the immune response currently evaluated in breast cancer; therefore, every attempt should be made to take advantage of their relationship with adipose tissue and, hence, leptin." (PMID 34868066, 2021). "In these studies, we analyzed the contribution of LEP (2548G>A) and LEPR (109 Lys>Arg and 223Gln>Arg) genes polymorphisms to the risk of breast cancer development." (PMID 33864589, 2021). "In cell culture, leptin acts as a growth-stimulating agent for breast cancer cells, promoting proliferation and repressing apoptotic pathways." (PMID 33987528, 2021). "Leptin and adiponectin are the most studied adipokines in breast cancer progression, but other adipokines were discovered contributing to breast cancer progression as well." (PMID 34944905, 2021). "Enrichment analyses of genes associated with both breast cancer DMFS and OS showed their involvement in natural killer cell mediated cytotoxicity, drug metabolism, muscle filament, ERBB2 and leptin signaling, aminoacid synthesis and B cell receptor signaling." (PMID 35096604, 2021). "The current review highlights the effects of breast adipose-derived estrogen, inflammatory mediators, leptin and decreased adiponectin on two aspects of breast cancer: initial events leading to carcinogenesis and progression." (PMID 33859943, 2021). "IONP-LPrA2 markedly decreased leptin-induced proliferation of breast cancer cells treated with chemotherapeutics." (PMID 34356668, 2021). "Taken together, these results indicated that LEP is significantly downregulated in human breast cancer." (PMID 34414945, 2021). "The blockage of Wnt/β-catenin signaling completely abrogated the leptin induced proliferation in breast cancer cells, suggesting its direct involvement in cancer cell proliferation." (PMID 34588926, 2021). "In an attempt to clarify how leptin‐stimulated autophagy induces lipid accumulation in breast cancer cells, we showed that leptin upregulated and activated SREBP‐1 in ER‐positive breast cancer cells as well as in tumor tissues." (PMID 33226729, 2021).
breast cancer (continued). "Leptin has also been shown to facilitate the growth and progression of neoplastic breast cancer cells by stimulating the pathway of Janus Kinase/Signal transducer and activator of transcription (JAK2/STAT3)." (PMID 33935708, 2021). "The aim of this article is to review the interaction between adipose tissue, through the expression of leptin and its receptor, and the adaptive immune system in breast cancer." (PMID 34868066, 2021). "LPrA-2, a fragment containing leptin site II and corresponding to amino acids 70–95 of human leptin, binds specifically and with high affinity to ObR and, acting as a leptin antagonist, inhibits leptin-related effects in breast cancer and other cancer types." (PMID 34356668, 2021). "Leptin enhances the proliferation of breast cancer cells by inhibiting the pro-apoptosis machinery, upregulating anti-apoptosis genes, modulating tumor microenvironment, and by increasing sensitivity to estrogen." (PMID 33482868, 2021). "In breast cancer cells, the expression of autophagy genes was found to involve estrogen receptors ERα signaling, since the inhibition of ERα abrogated leptin-induced autophagy." (PMID 34588926, 2021). "Similar results were observed following treatment with fatostatin, a pharmacological inhibitor of SREBPs, suggesting that SREBP‐1 critically contributes to induction of fatty acid synthesis under leptin stimulation in breast cancer cells." (PMID 33226729, 2021). "One of many proteins produced by adipose tissue is leptin, a cytokine that has been characterized as a growth factor in breast cancer." (PMID 33864589, 2021). "In this study, we present miR205 as a regulator of Med1, as well as decipher a ‘phospho-switch’ for Med1 which is regulated by ErB kinases Her2-EGFR, in leptin stimulated breast cancer." (PMID 34389732, 2021). "As previously stated, local levels of leptin are increased in obese adipose tissue and are believed to strongly contribute to breast cancer progression." (PMID 34944905, 2021). "The expression of leptin and its receptor can be used as an indicator of the diagnosis or prognosis of breast cancer." (PMID 35027962, 2021). "Leptin also has the ability to interfere with tamoxifen action in estrogen receptor positive breast cancer cell lines, due to its activation of ERK1/2 and STAT3 signal transduction pathways under estradiol stimulation." (PMID 33482868, 2021). "Because of its impact on inflammation, oxidative stress, cell proliferation, inhibition of apoptosis, angiogenesis and immune modulation, leptin seems to impact the development of cancer and specially of breast cancer in obese premenopausal women." (PMID 34684349, 2021). "Further exploration of the direct involvement of Her2 and EGFR in leptin-mediated Med1 phosphorylation showed increased activation of EGFR, ERK, and Her2 in leptin treated breast cancer cells." (PMID 34389732, 2021). "Since leptin increased the expression and activity of SREBP‐1, we questioned if leptin modulates the genes related with fatty acid synthesis in breast cancer cells." (PMID 33226729, 2021). "LEP is hypermethylated in breast cancer tissues in PrognoScan and R2-Kaplan Meier Scanner, and low LEP expression was correlated with poor prognosis." (PMID 34414945, 2021). "Immunohistochemical staining showed that cytoplasmic leptin was less frequently observed in breast cancers with unfavorable prognosis." (PMID 33799880, 2021). "Accordingly, CAF-derived leptin promotes malignant behaviors of breast cancer cells, in addition to secreting factors, which stimulate reprogramming of adjacent CAFs to produce more leptin and further amplify leptin signaling in cancer cells." (PMID 33535537, 2021).
breast cancer (continued). "Co-culture of obese ASCs with several ER+ breast cancer cell lines increased proliferation, migration, and invasion, an effect that was lost after silencing leptin in the ASCs." (PMID 33859943, 2021). "No data have been reported to date on the simultaneous expression of leptin and Ob-R in breast cancer or on the correlation with blood leptin levels." (PMID 34868066, 2021). "Breast cancer cells overexpressing miR-205 reduced leptin-mediated Med1, TFF1, and CATD overexpression whereas expression of miR-205-inhibitor potentiated the effect of leptin on Med1 expression." (PMID 34389732, 2021). "LPrA2, conjugated with iron-oxide nanoparticles, reduced leptin-induced chemoresistance for cisplatin, cyclophosphamide, paclitaxel, and doxorubicin in breast cancer." (PMID 33671547, 2021). "Since our results indicated that leptin exposure promotes a tamoxifen-refractory breast cancer cell phenotype, we investigated the kinases involved in tamoxifen-resistant breast cancer model to further understand the mechanistic underpinnings." (PMID 34389732, 2021). "The influence of LEP and LEPR genes polymorphisms on the body mass of women with breast cancer and control subjects was assessed." (PMID 33864589, 2021). "Among breast cancer patients, LEP expression was lower in the ≤51-year-old group than in the >51-year-old group." (PMID 34414945, 2021). "Preclinical and clinical breast cancer data already point to an interaction between adipose tissue (measured as BMI or via the leptin axis), the immune system, and the tumor." (PMID 34868066, 2021). "LDFI, as inhibitor of leptin activity, has been also used for the identification of the signals involved in exosome biogenesis in breast cancer cells and to elucidate the mechanisms driving cancer exosome production." (PMID 34356668, 2021). "In fact, in approximately 92% of breast cancer cases, most of the carcinoma cells showed overexpression of leptin, as seen in the intensity of staining, which was as marked as for adipocytes." (PMID 34868066, 2021). "The Kaplan Meier survival model was performed to evaluate the effect of E2 and leptin on prognosis of breast cancer patients." (PMID 34970222, 2021). "Leptin potentiates the release of corepressors and recruitment of coactivators to ER-responsive gene promoters in tamoxifen-treated breast cancer cells." (PMID 34389732, 2021). "For example, leptin was shown to transactivate ERα via signaling through ERK1/ERK2 in MCF7 breast cancer cells and increase estrogen production in the local microenvironment by stimulating aromatase expression in ASCs." (PMID 33859943, 2021). "In contrast, autophagy induction by leptin triggers a proliferative signal in estrogen receptor (ER)-positive breast cancer cells." (PMID 33535537, 2021). "The relative leptin expression level is high in head and neck cancer, peritoneal cancer, pancreatic cancer, cervical cancer, and breast cancer." (PMID 33799880, 2021). "Further studies will be needed to provide a better insight into how leptin‐induced alterations in fatty acid metabolism fuel the growth of breast cancer cells." (PMID 33226729, 2021). "Combined treatment with leptin and EGFR inhibitor, AG1478, inhibited leptin-induced Med1 phosphorylation in comparison to breast cancer cells treated with leptin alone." (PMID 34389732, 2021). "Then, in order to eliminate how E2 and leptin affected the prognosis of breast cancer patients, the relationship between E2, leptin, OS, and disease-free survival was discussed." (PMID 34970222, 2021). "And the relationship between E2, leptin, and clinicopathological parameters of postmenopausal patients with breast cancer was analyzed." (PMID 34970222, 2021). "Further, in order to clarify the value of leptin in prognosis assessment and verify the results of our analysis, a total of 702 postmenopausal cases with breast cancer were retrieved from The Cancer Genome Atlas (TCGA) database for prognostic analysis." (PMID 34970222, 2021).
breast cancer (continued). "Leptin, a hormone predominantly derived from adipose tissue, is well known to induce growth of breast cancer cells." (PMID 33226729, 2021). "Leptin also supports metastatic progression and tumor recurrence by increasing invasion and migration potential as well as stem-like characteristics in breast cancer cells." (PMID 34389732, 2021). "Tamoxifen treatment inhibited clonogenic potential (~70% inhibition) and anchorage-independent growth of breast cancer cells as expected but co-exposure of cells with leptin abrogated tamoxifen’s growth-inhibitory effects." (PMID 34389732, 2021). "Effects of leptin on induction of NF-κB phosphorylation in TAMs were also significantly attenuated by a pharmacological NF-κB inhibitor, and for breast cancer cells MCF-7, PI3K inhibitor affected the decrease of Akt phosphorylation." (PMID 34912237, 2021). "Herein, using public bioinformatics platforms, we evaluated the expression pattern of LEP in human breast cancer and the prognostic significance of LEP expression in breast cancer." (PMID 34414945, 2021). "Increased reservation of intracellular lipids was also observed in leptin-treated breast cancer cells as a direct consequence of upregulation of the genes related with fatty acid synthesis." (PMID 33535537, 2021). "High expression of leptin and an increase in circulating leptin levels further promote the progression of many cancers, such as breast cancer, pancreatic duct cancer and ovarian cancer." (PMID 34485124, 2021). "Our study provides evidence for the prognostic role of LEP in breast cancer and as a novel potential therapeutic target in such malignancies." (PMID 34414945, 2021). "The mechanisms through which leptin promotes cancer growth are best outlined in the setting of breast cancer." (PMID 33911195, 2021). "Leptin can promote invasion and lung metastasis of breast cancer cells by activating the PI3K/Akt-ATF-2 signaling pathway." (PMID 34787047, 2021). "Along with the evidence indicating the mitophagy-inducing effect of leptin, these findings suggest that leptin confers growth and survival advantages to breast cancer cells by improving mitochondrial quality and function." (PMID 33535537, 2021). "Then, the role of E2 and leptin in the prognosis assessment of postmenopausal breast cancer patients was performed." (PMID 34970222, 2021). "The adipocytes released leptin and IL-6 to promote metastasis in breast cancer cells by upregulating PLOD 2 expression via JAK/STAT and PI3K/AkT signaling." (PMID 34588926, 2021). "Leptin has been found to accelerate the occurrence and development of breast cancer, and obese women are more likely to suffer from breast cancer with high malignancy." (PMID 34485124, 2021). "The significant changes of LEP expression in transcription level between different types of breast cancer and normal breast tissues (Oncomine database)." (PMID 34414945, 2021). "In breast cancer, leptin and the leptin receptor are overexpressed in primary and metastatic lesions compared to non-cancer tissues." (PMID 33987528, 2021). "In breast cancer cells, short and long ObR isoforms are overexpressed and leptin has been shown to induce several signaling pathways and factors linked to the proliferation, migration, and invasion of cancer cells." (PMID 34356668, 2021). "In summary, this meta-analysis aimed to summarize association between the PON1 rs662, rs854560 LEP rs7799039 and LEPR rs1137101 polymorphisms and susceptibility to breast cancer." (PMID 34452542, 2021). "Leptin activation of autophagy is partly responsible for SREBP-1 induction that contributes to elevated lipogenesis in breast cancer cells." (PMID 33535537, 2021). "Leptin is considered a pro-tumorigenic protein whose circulating levels have been related to bad prognosis in obese breast cancer patients." (PMID 33763424, 2021). "Leptin can also signal through TGFB1 in breast cancer, which promotes metastasis and cancer stem cells behavior." (PMID 34202922, 2021).
breast cancer (continued). "In various studies, both in vivo and in vitro, the role of leptin in breast cancer progression has been addressed." (PMID 34944905, 2021). "In lung and breast cancer cells, leptin treatment has amplified the levels of soluble ICAM-1 by upregulating ERK, GSK3αβ, JAK1/2, STAT3 and focal adhesion kinase (FAK) signaling without affecting the expression of cell surface ICAM-1." (PMID 34588926, 2021). "With these inconsistencies, we downloaded data from the TCGA database to determine the correlation between leptin and prognosis of breast cancer patients." (PMID 34970222, 2021). "In this study, we examined the role of reprogramming of lipid metabolism and autophagy in leptin‐induced growth of breast cancer cells." (PMID 33226729, 2021). "An assessment of the comprehensive median expression of LEP across 15 analyses using the Curtis Breast microarray dataset showed that LEP expression was downregulated in most breast cancer types." (PMID 34414945, 2021). "LEP which inhibit apoptosis of breast cancer cells by coding leptin, while PLIN1 inhibits invasion, migration, and proliferation of cells." (PMID 34899291, 2021). "The stromal cell derived leptin is reported to support cancer metastasis in estrogen receptor positive and triple negative breast cancer cells by enhancing EMT via upregulating SERPINE 1, IL-6, MMP-2, SNAI 2, TWIST 1, vimentin and downregulating E-cadherin." (PMID 34588926, 2021). "It has been reported that adiponectin counteracts the leptin-induced migration and invasion of breast cancer cells." (PMID 34681797, 2021). "By contrast, women with a high BMI and breast cancer would have high leptin levels and low adiponectin levels." (PMID 34485137, 2021). "In this work, we show that leptin has a different effect on autophagy in breast cancer cell lines with different phenotypes." (PMID 33763424, 2021). "Analysis of breast cancer cells-derived tumors from mice treated with leptin, honokiol or a combination of leptin and honokiol showed higher expression of Med1 and phosphorylated Med1 in tumors from leptin-treated mice in comparison to honokiol-treated mice." (PMID 34389732, 2021). "In this study, we initially identified the expression levels of estradiol (E2) and leptin in breast cancer patients and healthy subjects with menopause." (PMID 34970222, 2021). "Breast cancer cells exposed to leptin showed decreased levels of miR-205 whereas tamoxifen treatment significantly increased the expression of miR-205." (PMID 34389732, 2021). "Leptin treatment had significantly upregulated IGF-1 in breast cancer cells via activated protein-1 (AP-1) transcription factor." (PMID 34588926, 2021). "In this meta-analysis, the associations of polymorphisms within paraoxonase 1 (PON1), leptin (LEP) and leptin receptor (LEPR) genes with susceptibility to breast cancer were comprehensively evaluated." (PMID 34452542, 2021). "GEPIA analysis showed that LEP expression in tumors was lower than that in normal tissues from the same breast cancer patients." (PMID 34414945, 2021). "Taken together, these results imply that autophagy activation is required for FAO‐driven ATP production by leptin in breast cancer cells." (PMID 33226729, 2021). "Binding of overexpressed leptin to leptin receptors (LEPRs) in peritumoral fat and breast cancer cells stimulates multiple signaling events, such as JAK2–STAT3, MAPK–ERK, and PI3K–AKT–mTOR pathways, thereby enhancing tumor proliferation and survival." (PMID 34063828, 2021). "A possible therapeutic strategy is inhibition of signaling pathways over-activated by leptin, which was proposed for ovarian cancer and breast cancer." (PMID 34202922, 2021).